DDAH1 (dimethylarginine dimethylaminohydrolase 1)
Diseases named in the same sentence as DDAH1 in open-access papers (continued):
Sharing a sentence is not in itself a finding about the gene and the disease.
melanoma (5 papers, 2018 to 2025). A malignant, usually aggressive tumor composed of atypical, neoplastic melanocytes. "Based on the published data approximately 80% of melanoma cell lines show overexpressed DDAH-1 that represent a potential target for control of nitric oxide production in melanoma cell line." (PMID 32613561, 2020). "A decrease in DDAH1 expression is only found in chromophobe renal cell carcinoma (a rare form of kidney cancer), melanoma and in testicular germ cell tumors." (PMID 31993367, 2019). "The research group demonstrated that DDAH1 is overexpressed in melanoma cell lines compared to normal human epidermal melanocytes and that cellular inhibition of DDAH1 by N5-(1-imino-2-chloroethyl)-L-ornithine (Cl-NIO) resulted in reduced nitric oxide production in the A375 melanoma cell line." (PMID 31993367, 2019).
acute myocardial infarction (4 papers, 2020 to 2024). Necrosis of the myocardium, as a result of interruption of the blood supply to the area. "Preclinical studies provide evidence that overexpression of DDAH1 protects from angiotensin-II-induced cardiovascular damage and attenuates left ventricular remodelling after acute myocardial infarction." (PMID 39200175, 2024). "MnSOD expression was elevated by an endogenous cardioprotective enzyme, dimethylarginine dimethylaminohydrolase 1 (DDAH1), to attenuate acute myocardial infarction (MI) by suppressing apoptosis and oxidative stress in cardiomyocytes." (PMID 36555531, 2022).
Hepatic steatosis (4 papers, 2022 to 2025). Steatosis is a term used to denote lipid accumulation within hepatocytes. "Compared with control mice (Ddah1 f/f), Ddah1 HKO mice exhibited significantly attenuated hepatic steatosis after fasting." (PMID 42058454, 2025). "We consistently reported that DDAH1 exerts protective effects in different models, including high-fat diet-induced hepatic steatosis, PM2.5-induced lung injury, and pressure-overloaded hearts." (PMID 39334728, 2024). "We previously showed that deletion of Ddah1 exacerbated hepatic steatosis and insulin resistance in obese mice." (PMID 35624743, 2022). "In addition, overexpression of DDAH1 in hepatocytes exacerbated hepatic steatosis in fasted mice, coinciding with FABP1 upregulation and autophagy inhibition." (PMID 42058454, 2025). "Upregulation of DDAH1 may improve liver fibrosis and hepatic steatosis in obese mice by reducing the expression of S100A11." (PMID 40646803, 2025). "We previously demonstrated that DDAH1 has profound effects on cellular redox state and Ddah1 deletion exacerbated high-fat diet (HFD)-induced hepatic steatosis and oxidative stress in mice." (PMID 35624743, 2022).
schizophrenia (4 papers, 2022 to 2025). A major psychotic disorder characterized by abnormalities in the perception or expression of reality. "DDAH1 alleles are associated with the risk of developing autistic spectrum disorder or obsessive-compulsive disorder, and animal models of autism and schizophrenia endophenotypes present with increased DDAH1 levels." (PMID 36233204, 2022). "The lost association of DDAH1 expression with CG promoter motif genes may mirror the overexpression of TET1 in cortical structures in patients with schizophrenia or bipolar disorder." (PMID 36233204, 2022). "Proteome analysis revealed reduced DDAH1 expression in the anterior cingulate cortex of patients with schizophrenia, with functional annotation in oxidative stress processes." (PMID 41017816, 2025). "SNPs in DDAH1 and DDAH2 are associated with schizophrenia, bipolar disorder, depression, anxiety, and alcohol dependence, as well as broader traits such as neuroticism, guilt feelings, and sleep quality parameters." (PMID 41017816, 2025). "In line, normal DDAH1 expression levels have previously been shown in chronic schizophrenic patients, while DDAH1 upregulation was found in patients with short-term schizophrenia." (PMID 36233204, 2022). "Specifically, we evaluated evidence of DDAH1 and DDAH2 involvement in regulating processes associated with major psychotic disorders, schizophrenia, and bipolar disorder." (PMID 36233204, 2022). "However, elevated DDAH1 levels have also been reported in animal models exhibiting schizophrenia- or depression-related phenotypes with learning and memory deficits, as well as in models of sleep deprivation and methamphetamine toxicity." (PMID 41017816, 2025). "In addition, a strong downregulation of the hsa-miR-219-5p that is suggested to control DDAH1 expression was observed in schizophrenia patients." (PMID 36233204, 2022). "Compared to healthy controls, reduced nitrergic neurons, NOS activity, dysregulation in the enzymes regulating the bioavalibility of L-arginine, dimethylarginine dimethylaminohydrolase 1 (DDAH1) and arginase have been observed in schizophrenia patients." (PMID 40553248, 2025). "The dataset GSE112523 combines data from subjects with schizophrenia, bipolar affective disorder, and non-psychiatric controls; thus, it was further analyzed to compare DDAH1 and DDAH2 co-expressed gene sets in these psychiatric disorders." (PMID 36233204, 2022).
Sepsis (4 papers, 2010 to 2024). Sepsis is defined as life-threatening organ dysfunction caused by a dysregulated host response to infection. "The loss of DDAH-1 function in a murine model of sepsis increased ADMA, reduced NO signaling, and worsened vascular pathophysiology including endothelial function." (PMID 20421938, 2010).
Stroke (4 papers, 2016 to 2025). Sudden impairment of blood flow to a part of the brain due to occlusion or rupture of an artery to the brain. "Recently, several studies have suggested that DDAH1 level was correlated with amplified risk of stroke and CHD." (PMID 35958279, 2022). "A large body of evidence has indicated that the loss of function DDAH1 can directly relate to the rising morbidity of the coronary heart disease, thrombosis, and stroke." (PMID 35958279, 2022). "Studies have demonstrated that DDAH1 variants are associated with increased plasma ADMA and increased risk of thrombosis, stroke and coronary artery disease (CAD) in humans." (PMID 26786611, 2016). "By comparing Ddah1 knockout, transgenic, and wild-type mice, DDAH1 was found to promote adult neurogenesis and cognitive recovery after stroke by regulating the hypoxia-inducible factor 1α via NO, which in turn regulates genes involved in acetylcholine-related neurogenesis and repair." (PMID 41017816, 2025). "Furthermore, the roles of other stroke-associated genes, such as SAMHD-1, DDAH-1, HMOX1, LTC4S, ACTB, KPNA2, and JUN, in mediating stroke secondary to SARS-CoV-2 infection are required to be further explored experimental using COVID-19 patient samples or SARS-CoV-2 animal models." (PMID 33732102, 2021). "Moreover, the expression level of several stroke-associated inflammatory genes, such as VCAM-1, SMAHD-1, and DDAH1, were significantly upregulated in COVID-19 positive patients, indicating that the inflammatory response may play potential roles in mediating COVID-19-associated stroke." (PMID 33732102, 2021).
cardiac hypertrophy (3 papers, 2020 to 2023). "In contrast, DDAH1 is crucial in reducing myocardial hypertrophy and ventricular remodeling under stress conditions." (PMID 37559135, 2023). "DDAH1 attenuates ventricular remodeling and cardiac hypertrophy under stress conditions via regulating subcellular NO signaling." (PMID 33041871, 2020).
chronic kidney disease (3 papers, 2011 to 2025). Impairment of the renal function secondary to chronic kidney damage persisting for three or more months. "Also, DDAH1 is essential for maintaining renal function, especially in diabetes and chronic kidney disease, and increasing its expression in kidney can alleviate DKD symptoms." (PMID 41318413, 2025).
Cirrhosis (3 papers, 2017 to 2022). A chronic disorder of the liver in which liver tissue becomes scarred and is partially replaced by regenerative nodules and fibrotic tissue resulting in loss of liver function. "Hepatic DDAH-1 was significantly decreased in rats with cirrhosis, reflecting increased availability of ADMA and NO synthesis inhibition." (PMID 35831335, 2022). "Hepatic DDAH-1 was significantly decreased in rats with cirrhosis compared to normal rats (p < 0.001)." (PMID 35831335, 2022). "Administration of OCA in a model of cirrhosis induced by bile duct ligation (BDL) induced an increase in DDAH-1 protein and an increase in serum ADMA, while in the present study regular biliary clearance allows ADMA to be eliminated and OCA did not alter DDAH-1 expression or activity during I/R." (PMID 29346429, 2018). "Hepatic DDAH1 expression is reduced in cirrhosis patients and rat models." (PMID 29263339, 2017). "This suggests a potential role for the impact of oxidative stress on the DDAH1-ADMA axis and resulting changes in intrahepatic vascular tone in cirrhosis patients." (PMID 29263339, 2017). "This study aimed to study the bile duct ligated rat model of cirrhosis with PH and inflammation, to determine the effects of IFX therapy on severity of PH, and its role in modulating oxidative-stress and the DDAH1-ADMA axis." (PMID 29263339, 2017).
depression (3 papers, 2021 to 2025). "Finally, paroxetine treatment normalized DDAH1 expression in the hypothalamus and amygdala, reduced oxidative stress, and alleviated depressive-like behaviors, underscoring its potential in treating conditions that involve both depression and oxidative stress." (PMID 41017816, 2025). "Oxidative stress (enriched by HSP90 and DDAH1): Oxidative stress refers to the biologically damaging effects of free radicals, there is evidence suggesting that oxidative stress may be increased in a number of psychiatric disorders, including depression." (PMID 34658947, 2021).
renal fibrosis (3 papers, 2020 to 2024). A final common manifestation of a wide variety of chronic kidney diseases characterized by glomerulosclerosis and tubulointerstitial fibrosis. "Upregulation of miR-21 involves different mechanisms in promoting renal fibrosis, such as the decrease in dimethylarginine dimethylaminohydrolase 1 (DDAH1) expression." (PMID 38474021, 2024). "To further determine the effect of renal ADMA on renal fibrosis, we injected nonsense control (NC), Ddah1 or Ddah2 siRNA to the UUO kidney through the left ureter." (PMID 32794631, 2020). "An alternative mechanism of miR-21-induced renal fibrosis may involve the decrease of dimethylarginine dimethylaminohydrolase 1 (DDAH1) activity/expression." (PMID 37760798, 2023). "Thus, we conclude that renal ADMA is antifibrotic, which is in line with the conclusion provided by previous in vitro studies or indirect evidence using type I PRMT inhibitors or kidney‐specific deletion of Ddah1 gene in mouse models of renal fibrosis." (PMID 32794631, 2020).
Right ventricular hypertrophy (3 papers, 2020 to 2021). In this case the right ventricle is more muscular than normal, causing a characteristic boot-shaped (coeur-en-sabot) appearance as seen on anterior- posterior chest x-rays. "However, DDAH1 knockout mice exposed to chronic hypoxia show the same extent of right ventricular hypertrophy as their wildtype littermates." (PMID 34945057, 2021). "In the Ddah1−/− mouse, ADMA concentrations in lung tissue and in plasma were elevated by about 50%, and a slight, but significant right ventricular hypertrophy was noted even under normoxic conditions." (PMID 33281630, 2020). "We measured ADMA concentration in plasma and lungs, DDAH1 and DDAH2 mRNA and protein expression in the lungs, right ventricular systolic pressure (RVSP), right ventricular hypertrophy by the Fulton index, and cardiomyocyte hypertrophy by dystrophin staining of the heart." (PMID 33281630, 2020). "Downregulation of DDAH1 expression and activity may be involved in this; however, knockout of the Ddah1 gene does not modify the hypoxia-induced pathophysiological changes of pulmonary blood pressure and right ventricular hypertrophy, possibly due to compensatory upregulation of DDAH2 protein." (PMID 33281630, 2020). "However, the effects of chronic hypoxia on RVSP and right ventricular hypertrophy were not significantly different between WT and Ddah1−/− mice in our study, which corresponds to the absence of a significant difference in lung tissue ADMA concentration between both genotypes in hypoxia." (PMID 33281630, 2020).
Anxiety (2 papers, 2023 to 2025). Intense feelings of nervousness, tension, or panic often arise in response to interpersonal stresses. "Anxiety-like phenotypes in rats induced by monosodium L-glutamate treatment also manifested with reduced hippocampal DDAH1 levels." (PMID 41017816, 2025).
asthma (2 papers, 2014 to 2018). "ADMA and DDAH1 are of increasing interest in the fields of heart and lung research, and are associated with asthma, shock and cancer." (PMID 29415054, 2018). "We determined the effect of DDAH1 overexpression on development of allergic inflammation in a mouse model of asthma." (PMID 24465497, 2014). "Our data reveal that expression of DDAH1 and DDAH2 is decreased in the lungs in a mouse model of asthma, and overexpression of DDAH1 attenuates allergen-induced airway inflammation." (PMID 24465497, 2014). "DDAH1 and DDAH2 are responsible for metabolism of over 90% of ADMA in vivo, and our data support a role for DDAH downregulation in asthma pathogenesis." (PMID 24465497, 2014). "We determined the expression of DDAH1 and DDAH2 in the lungs in a mouse model of asthma." (PMID 24465497, 2014).
autism (2 papers, 2022 to 2025). Persistent deficits in social interaction and communication and interaction as well as a markedly restricted repertoire of activity and interest as well as repetitive patterns of behavior. "Additionally, DDAH1 has emerged as a candidate in autism spectrum and obsessive-compulsive disorders." (PMID 41017816, 2025).
autism spectrum disorder (2 papers, 2022). A spectrum of developmental disorders that includes autism, and Asperger syndrome. "For example, Slc1a2, Prdm16, Kank1 and Ddah1 were target genes of Dbx2, the high expression of Slc1a2 was found to reduce the risk for PD in a Chinese cohort and the other genes are associated with cognitive function, autism spectrum disorder and depression-like behavior, respectively." (PMID 36142685, 2022).
bipolar disorder (2 papers, 2022 to 2025). A disorder of the brain that causes unusual shifts in mood, energy, activity levels and the ability to carry out day-to-day tasks. "Genetic variants of DDAH1 are linked to treatments, such as lithium in patients with bipolar disorder and amphetamine response." (PMID 41017816, 2025). "The greatest overlap between the co-expressed gene set and the “DDAH1 cluster” was identified in patients with bipolar affective disorder." (PMID 36233204, 2022). "In patients with bipolar disorder, the enrichment is also lost in the DDAH1 co-expressed gene set." (PMID 36233204, 2022). "The co-expression of DDAH1 and DDAH2 with the genes annotated with these terms was identified in dorsolateral prefrontal cortex samples in non-psychiatric controls but was lost both in schizophrenic and bipolar disorder patients." (PMID 36233204, 2022). "No DO terms were enriched in genes co-expressed with DDAH1 in the patients with bipolar affective disorder." (PMID 36233204, 2022). "We found that the large group of genes for which involvement in DDAH1-related functions was previously identified (n = 45) is co-expressed with DDAH1 in the bipolar affective disorder group stochastically, and no significant GO term enrichment results were revealed in this gene set." (PMID 36233204, 2022).
Cerebral ischemia (2 papers, 2020 to 2022). Restriction of arterial blood supply to the brain associated with insufficient oxygenation to support the metabolic requirements of the tissue. "Dimethylarginine dimethylaminohydrolase 1 (DDAH1) protects against cerebral ischemia injury via regulating the level of asymmetric dimethylarginine (ADMA)." (PMID 35509834, 2022). "However, AdipoRon pretreatment attenuated the cerebral ischemia–induced injury in both DDAH1−/− and DDAH1+/+ rats and also enhanced the APR1/APPL1/pAMPK signaling." (PMID 35509834, 2022). "Thus, functionality of DDAH1 may be an important, in part genetically influenced determinant of the incidence of cerebral ischemia after SAH." (PMID 33271854, 2020). "This suggested that DDAH1/ADMA might not contribute to the pathogenesis of cerebral ischemia purely through modulating APN levels." (PMID 35509834, 2022). "This suggested that DDAH1/ADMA might not affect the process of cerebral ischemia purely via regulating APN level." (PMID 35509834, 2022).
colorectal adenocarcinoma (2 papers, 2017 to 2020). The most common type of colorectal carcinoma. "Furthermore, analysis of the TCGA-COAD RNASeq dataset (461 colorectal adenocarcinoma specimens) also revealed a significant negative correlation between DDAH1 and miR-193b." (PMID 29070803, 2017).
congestive heart failure (2 papers, 2013 to 2020). Failure of the heart to pump a sufficient amount of blood to meet the needs of the body tissues, resulting in tissue congestion and edema. "DDAH1 plays an important role in regulating the cardiovascular function and risk factors of congestive heart failure (CHF) by maintaining cardiovascular NO/cGMP/PKG signaling." (PMID 32982723, 2020). "Thus, modulating DDAH1 activity through FXR receptor agonists such as UDCA could be a therapeutic target for treating reduced nitric oxide bioavailability in congestive heart failure and other cardiovascular diseases." (PMID 23878601, 2013).
diabetic nephropathy (2 papers, 2020 to 2022). "DDAH1 mediates renal tissue protection in diabetic nephropathy via the ADMA-NOS3-interaction." (PMID 36561848, 2022). "Interestingly, a recent study showed that reduction of renal ADMA levels by intrarenal injection of adenovirus‐expressing DDAH‐1 ameliorates diabetic nephropathy." (PMID 32794631, 2020).
heart failure (2 papers, 2013 to 2019). Inability of the heart to pump blood at an adequate rate to meet tissue metabolic requirements. "Because DDAH activity is reduced in the failing heart and this likely contributes to increased ADMA levels and endothelial dysfunction, identifying new mechanisms to increase DDAH1 expression or activity may be clinically relevant in the treatment of heart failure." (PMID 23878601, 2013). "Given the importance of DDAH1 in maintaining homeostasis of the cardiovascular system, particularly in attenuating cardiovascular disease and heart failure, potential negative impacts of inhibition of DDAH1 must be considered." (PMID 31993367, 2019).
Hyperglycemia (2 papers, 2017 to 2023). An increased concentration of glucose in the blood. "We hypothesized that acute hyperglycemia in critically ill patients reduces DDAH1 activity, thereby increasing plasma ADMA concentration and reducing endothelial-dependent vasodilatation." (PMID 37005603, 2023). "Moreover, previous studies in a rodent model have reported that the activity of the main enzyme that regulates ADMA concentration in plasma, dimethylarginine-dimethylaminohydrolase 1 (DDAH1), is down-regulated by hyperglycemia." (PMID 37005603, 2023). "To further elucidate the effect of intrauterine exposure to maternal hyperglycemia on ADMA metabolism in offspring, we studied the expression of protein arginine methyltransferases (PRMTs) and dimethylarginine dimethylaminohydrolase (DDAH1 and 2) in metabolic tissues by rt-PCR." (PMID 28218737, 2017).